IL13RA2 (interleukin 13 receptor subunit alpha 2)
Diseases named in the same sentence as IL13RA2 in open-access papers (continued):
Sharing a sentence is not in itself a finding about the gene and the disease.
cancer (continued). "However, studies on other cancers revealed that IL-13Rα2 expression requires AP-1/c-jun signaling and this pathway was shown to be quiescent in non-malignant cells, which, similar to the findings of this study, were refractory to HDAC inhibitor-induced IL-13Rα2 expression." (PMID 37345109, 2023). "IL-13/IL13Rα2 activation of PTP1B was independent of EGFR activation and was critical for migration and invasion of cancer cells." (PMID 32098194, 2020). "Unlike the other IL-13 receptor, IL-13Rα2, data on IL-13Rα1 in the GIT cancers are limited and inconclusive." (PMID 32512917, 2020). "IL‐13Rα2 is overexpressed in ∼76% of GBM but is not detected in normal brain tissue or normal immune cells, making it an attractive target for the receptor‐directed cancer therapy." (PMID 38685487, 2024). "The expression of IL-13Rα2 mRNA and protein was then analysed in prostate non-cancer (PNT2) and cancer (androgen-dependent (LNCaP) and androgen-independent with a high metastatic potential (DU145 and PC-3)) cell lines via RT-PCR and immunoblotting, respectively." (PMID 36830725, 2023).
infection (11 papers, 2009 to 2023). The state of being infected such as from the introduction of a foreign agent such as serum, vaccine, antigenic substance or organism. "In fact, we have observed that IL-13Rα2 expression when highly upregulated coincides with the resistance to secondary infection at 2 wppt." (PMID 33276813, 2020). "Treatment of mice with IL-13Rα2 abrogated the immune response to E. caproni primary infection despite the presence of rIL-25." (PMID 33276813, 2020). "The majority of the deaths occurred during the acute phase of the infection when the host immune response peaks and before additional protective mechanisms like IL-10 or the IL-13 decoy receptor (IL-13Rα2) are fully activated." (PMID 25211233, 2014). "Amelioration of altered airway responses after secondary infection could also be achieved with administration of an IL-13Rα2 fusion protein, blockade of IgE, blockade of IL-33 signaling, or inhibition of STAT6 during the primary infection." (PMID 35493465, 2022). "Furthermore, our results suggest that IL-13Rα2 plays an important role in the regulation of the response to primary infection." (PMID 33276813, 2020). "Moreover, anti-IL13Rα2 mAb effectively inhibited the infection of U251MG cells by Ad5FFscFv47-CMV-GFP in a competitive assay." (PMID 26656559, 2015). "Th2 response genes such as Il13ra2, Il4ra and Bcl6 are upregulated in the NPH, suggesting these are crucial genes to fight off infection by induction of parasite-specific IgG and IgE, smooth-muscle cell contractility, intestinal permeability and resistin-like molecule (RELM)-beta secretion." (PMID 36883013, 2023). "Expression of IL-13Rα2 in Gli36.IL-13Rα2-GFP was not altered by the infection." (PMID 29203859, 2017).
CNS tumors (4 papers, 2022 to 2025). "IL13RA2 is an attractive TAA present in several CNS tumors and has been validated as an immunotherapeutic target in adult GBM31,32." (PMID 39711568, 2024). "Furthermore, elevated IL13RA2 gene expression was seen in pHGG compared to low-grade CNS tumors." (PMID 39711568, 2024). "In pediatric CNS tumors, B7-H3 and GD2 are the most frequently observed antigens, followed by IL13Rα2, with HER2 and EphA2 being less common." (PMID 40895575, 2025). "Currently, there are a limited number of CAR T-cell clinical trials for children with CNS tumors, all at phase I. Targets include HER2, B7 homolog 3 (B7H3), EGFR806, the disialoganglioside GD2 and IL13Rα2." (PMID 35155252, 2022).
benign tumors (1 paper, 2018). "The IL13Rα2 expression level is lower in these benign tumors than that of the MPNSTs, but it is still present in detectable amounts, suggesting the opportunity to target those benign tumors with IL13 conjugated liposomes for efficacious therapy." (PMID 29304038, 2018).
infectious disease (1 paper, 2019). A disorder directly resulting from the presence and activity of a microbial, viral, or parasitic agent in humans. "Since IL-13 signaling and its unique receptor IL-13Rα2 contribute to the prolongation of inflammation in various infectious diseases, this study might be useful in seeking potential therapeutic targets to prevent Th2 cytokine-related diseases." (PMID 31010051, 2019).
IL13RA2 also shares sentences with these, for which no sentence is quoted: medulloblastoma (9 papers); adrenocortical carcinoma (8); viral infection (4); head and neck squamous cell carcinoma (3); inflammation (2); Kaposi's sarcoma (2); liver cancer (2); mesothelioma (2); multiple myeloma (2); oligodendroglioma (2); acute lymphoblastic leukemia (1); acute myeloid leukemia (1); AIDS (1); airway hyperresponsiveness (1); Airway obstruction (1); benign vascular tumor (1); bronchiolitis (1); Clear Cell Renal Cell Carcinoma (1); co-infection (1); Crohn disease (1); diffuse midline glioma (1); Ewing’s family tumors (1); head and neck tumor (1); helminth infections (1); hemangioma (1); hematological cancers (1); hematological malignancies (1); Hermansky-Pudlak syndrome (1); immune deficiency (1); influenza (1).
A further 23 diseases each share a sentence with IL13RA2 in 1 paper.